ERCC2 (ERCC excision repair 2, TFIIH core complex helicase subunit)
Diseases named in the same sentence as ERCC2 in open-access papers (continued):
Sharing a sentence is not in itself a finding about the gene and the disease.
ovarian carcinoma (continued). "The objective of this study was to establish the role of two functional polymorphisms of a DNA repair gene ERCC2 in the risk of breast or ovarian cancer." (PMID 18454848, 2008). "Concerning ovarian cancer, a significant increase in the risk was found for heterozygous ERCC2 Lys751Gln and who had menarche before 13 years old (OR = 6.03; 95% CI = 1.02–35.78)." (PMID 18454848, 2008). "Heterozygous ERCC2 Lys751Gln with WHR = 0.85 also exhibited an upward tendency in the risk of ovarian cancer (OR = 5.68; 95% CI = 0.94–34.25)." (PMID 18454848, 2008). "However, platinum-based chemotherapy in ovarian cancer patients with the ERCC2 Lys751Gln polymorphism was associated with a reduced risk of death, particularly among those with heterozygous genotypes." (PMID 40777111, 2025). "In conclusion, our results indicated that ERCC1, XPC and ERCC2 might influence ovarian cancer susceptibility." (PMID 29669843, 2018). "However, more comprehensive studies with larger independent cohorts should be performed to unveil the real relationship between these significant genetic variations in the ERCC1, XPC and ERCC2 and ovarian cancer risk." (PMID 29669843, 2018). "In conclusion, our study indicated that the ERCC1, XPC and ERCC2 might correlate to ovarian cancer susceptibility." (PMID 29669843, 2018). "Moreover, a significant association was found between the ERCC2 rs238406 polymorphism and increased risk of ovarian cancer under dominant genetic model (adjusted OR = 2.07, 95% CI = 1.07–4.01, P=0.032)." (PMID 29669843, 2018). "In case of ERCC2, panel sequencing of 1345 index cases from 587 German, 405 Lithuanian and 353 Czech families with breast and ovarian cancer (BC/OC) predisposition revealed 25 mutations (3 frameshift, 2 splice-affecting, 20 missense), all absent or very rare in the ExAC database." (PMID 27504877, 2016). "Finally, with respect to the excision repair genes, previous studies reported a correlation between severe neutropenia and the rs1799793 (934G > A) variant A-allele in ERCC2 in 104 ovarian cancer patients receiving a cisplatin-cyclophosphamide regimen." (PMID 25881102, 2015). "The ERCC2-Gln/Gln genotype increased 5 times the risk of ovarian cancer formation." (PMID 26526682, 2015). "An attempt was undertaken in the presented study to determine whether single nucleotide polymorphism in the DNA repair pathway (ERCC2-Lys751Gln) was associated with the risk of ovarian cancer in Polish women." (PMID 26526682, 2015). "In conclusion, our results indicate that the ERCC2 Lys751Gln SNP may be involved in the susceptibility of ovarian cancer in the Polish population." (PMID 26526682, 2015). "Heterozygous ERCC2 Asp312Asn with BMI > 25 exhibited a significant increase in ovarian cancer risk (OR = 3.5; 95% CI = 1.00–12.26), while heterozygous ERCC2 Lys751Gln with body mass index (BMI) < 25 exhibited an upward tendency in ovarian cancer risk (OR = 5.64; 95% CI = 0.93–33.99)." (PMID 18454848, 2008). "In addition, XPC rs2228001 and ERCC2 rs238406 had statistically significant association with the increased risk of ovarian cancer under dominant genetic model (adjusted OR = 1.72, 95% CI = 1.02–2.92, P=0.043 and adjusted OR = 2.07, 95% CI = 1.07–4.01, P=0.032 respectively)." (PMID 29669843, 2018). "In particular, the correlation between the expression of ERCC1 and ERCC2 in 42 Ovarian cancer patient-derived xenografts (PDX), as measured by quantitative RT-PCR, was r = 0.71, p-value = 1.4 × 10−7." (PMID 34837938, 2021). "miR-770 functions as an anti-oncogene and promotes chemosensitivity in ovarian cancer by downregulating ERCC2." (PMID 30524203, 2018). "They showed that miR-770-5p inhibits cisplatin chemoresistance by targeting ERCC2 in vivo and in vitro in human ovarian cancer." (PMID 28333152, 2017).
ovarian carcinoma (continued). "We found that the ERCC2 Lys751Gln polymorphism was significantly associated with ovarian cancer, while the ERCC2 Asp312Asn and Arg156Arg polymorphisms did not exhibit any relationship with susceptibility to ovarian cancer." (PMID 40777111, 2025). "In the present study, we performed a hypothesis-based association to explore the impact of SNPs in these core genes (XPA, XPC, XPG, ERCC1, ERCC2, and ERCC4) on the risk of ovarian cancer by genotyping a pool of 17 SNPs in 89 patients and 356 controls." (PMID 29669843, 2018). "Because the effects of miR-770-5p on DNA repair might explain its ability to modulate cisplatin-resistance in ovarian cancer, we examined the role of ERCC2 in this repair process." (PMID 27449101, 2016). "Heterozygous individuals ERCC2 Asp312Asn who did not take oral contraceptives had a significant increase in the risk of ovarian cancer (OR = 2.16; 95% CI = 1.08–4.33)." (PMID 18454848, 2008). "Therefore, the ERCC2 Arg156Arg (C/A) polymorphism does not increase the risk of ovarian cancer, cervical cancer, or endometrial cancer." (PMID 40777111, 2025). "Therefore, we conducted genotyping for 17 SNPs of six NER core genes (XPA, XPC, XPG, ERCC1, ERCC2, and ERCC4) in 89 ovarian cancer cases and 356 cancer-free controls." (PMID 29669843, 2018).
colorectal cancer (21 papers, 2008 to 2024). A primary or metastatic malignant neoplasm that affects the colon or rectum. "In the current study, we examined the association of SNPs in the genes XRCC1-rs25487, ERCC1-rs11615, ERCC2-rs238406, and ERCC2-rs13181 with colorectal cancer (CRC) risk, relapse-free survival (RFS), overall survival (OS), and toxicity during chemotherapy." (PMID 32397974, 2020). "Several ERCC2 variants have been correlated to gastric cancer risk, and ERCC2 expression levels may serve as a marker for chemoresistance in colorectal cancer." (PMID 37568604, 2023). "The present retrospective cohort study aimed at investigating whether MLH1,APEX1,MUTYH,OGG1,NUDT1,XRCC5, XPA, and ERCC2 single nucleotide polymorphisms (SNPs) are associated with colorectal cancer (CRC) in Chinese population with Lynch syndrome." (PMID 29664240, 2018). "However, three studies illustrated that patients with the ERCC2 751 polymorphic allele or genotype had a reduced response to chemotherapy in osteosarcoma and colorectal cancer patients, while other studies have shown the opposite results." (PMID 29980176, 2018). "In addition, the ERCC2/XPD variant Lys751Gln (rs13181) was associated with the response to treatment with 5-fluorouracil and oxaliplatin in colorectal cancer patients." (PMID 18547414, 2008). "The altered expression of ERCC genes has been associated with increased risk of colorectal cancer, where ERCC1, ERCC2 and ERCC5 were overexpressed, and invasive cervical carcinoma, where ERCC1 and ERCC2 were underexpressed." (PMID 35955506, 2022). "First, from online databases, colorectal cancer (CRC) patients exhibited significantly reduced survival when ERCC2 was overexpressed in colon tumors." (PMID 33809839, 2021). "In patients with colorectal cancer ERCC1, ERCC2, ERCC5 and DDB2 genes are more expressed in tumor tissue than in matched normal tissue, while ERCC4 is downregulated." (PMID 35955506, 2022). "In colorectal cancer, ERCC2 overexpression failed to predict the survival time of patients receiving adjuvant chemotherapy, but the expression and prognosis ability of ERCC2 mRNA in GC are unreported." (PMID 30417012, 2018).
glioma (15 papers, 2014 to 2025). A benign or malignant brain and spinal cord tumor that arises from glial cells (astrocytes, oligodendrocytes, ependymal cells). "Researchers found that the odds ratio (OR) for glioma increases significantly in the population carrying homozygous variants of ERCC2 K751Q (QQ)." (PMID 37208656, 2023). "To date, a number of studies have implicated the role of genetic polymorphism within ERCC2 gene in various cancers, such as gastric, pancreatic, glioma, bladder, and hepatocellular carcinoma." (PMID 33171788, 2020). "The ERCC2 rs13181 polymorphism has been documented to be associated with a higher susceptibility to glioma among the Chinese population." (PMID 28388903, 2017). "Meta-analysis of the association of ERCC1 C8092A and ERCC2 Lys751Gln polymorphism with the risk of glioma." (PMID 24763305, 2014). "Several previous studies have reported the role variant of ERCC1 rs3212986 and ERCC2 rs13181 polymorphisms in the risk of glioma, but the results of these studies are inconsistent." (PMID 25674148, 2014). "Stratified analysis of the association of ERCC2 Lys751Gln polymorphism with the risk of different type of glioma." (PMID 24763305, 2014). "When conducting stratified analysis by ethnicity, ERCC1 rs3212986AA, ERCC2 rs13181 GT and TT genotypes was associated with increased risk of glioma in Chinese population." (PMID 25674148, 2014). "When deleting a study in the Chinese population, the ERCC2 Lys751Gln polymorphism showed significant effects on the risk of glioma, but the significance was much less (Z = 2.10, P = 0.04, OR = 0.89, 95%CI: 0.79–0.99)." (PMID 24763305, 2014). "In this study, we performed a meta-analysis of the available studies in different ethnic populations to evaluate the effects of ERCC1 C8092A and ERCC2 Lys751Gln polymorphisms on the susceptibility to glioma." (PMID 24763305, 2014). "There was no significant heterogeneity between pooled studies, and thus we performed a fixed-effect model to assess the association between ERCC1 rs3212986 and ERCC2 rs13181 and risk of glioma." (PMID 25674148, 2014). "Our study suggests that ERCC1 rs3212986 and ERCC2 rs13181 showed different effect on the risk of glioma across different populations." (PMID 25674148, 2014). "In a Chinese population the variants of ERCC2 Lys751Gln polymorphism was significantly different between glioma cases and controls (χ2 = 6.015, P = 0.014)." (PMID 24763305, 2014). "Evidently, numerous studies have been done to identify the association of ERCC1 C8092A and ERCC2 Lys751Gln polymorphisms with the risk of glioma in different ethnic populations." (PMID 24763305, 2014). "A significant association of ERCC2 Lys751Gln polymorphism with the risk of glioma was identified in the Caucasian population under recessive model (OR = 0.87; 95% CI: 0.78–0.98, P = 0.02), but not in the Chinese population." (PMID 24763305, 2014). "Among these genes, excision repair cross-complementing group 1 (ERCC1) and ERCC2 gene are considered to be related with the susceptibility of glioma due to their roles as rate limiting enzymes in association to NER." (PMID 24763305, 2014). "The AA genotype of ERCC1 C8092A might be associated with a higher risk of adult glioma than the CA and CC genotypes and that the risk allele of ERCC2 K751Q confered a significant susceptibility to adult glioma, especially in Asian populations." (PMID 26249370, 2015). "Similarly, we found that ERCC2 rs13181 GT and TT genotypes were significantly associated with increased risk of glioma in Chinese population, with ORs(95%CI) of 1.47(1.17-1.85) and 1.50(1.02-2.22)." (PMID 25674148, 2014). "Therefore, we cannot explicitly estimate the effects of ERCC2 Lys751Gln polymorphism on the risk of different kinds of glioma in our study." (PMID 24763305, 2014). "And the TT genotype of ERCC2 Lys751Gln polymorphism may decrease the risk of glioma in the Caucasian population." (PMID 24763305, 2014).
glioma (continued). "The overall frequency of ERCC2 751Gln allele was 59.66% for glioma cases and 61.27% for controls." (PMID 24763305, 2014). "Therefore, we aimed to conduct a meta-analysis to investigate the role of ERCC1 rs3212986 and ERCC2 rs13181 on the risk of glioma." (PMID 25674148, 2014). "Therefore, an increasing amount of studies attempt to identify the association of ERCC1 and ERCC2 polymorphisms on the susceptibility of glioma." (PMID 24763305, 2014). "Therefore, the finding between ERCC2 Lys751Gln polymorphism and the risk of glioma in Caucasian population should be addressed with caution." (PMID 24763305, 2014). "In addition, among Caucasians, glioma cases were significantly more likely than controls to be homozygous for ERCC2 Lys751Gln polymorphism (OR = 3.2, 95% CI: 1.1–9.3)." (PMID 24763305, 2014). "However, TT genotype of ERCC2 Lys751Gln polymorphism might decrease the risk of glioma in Caucasian population." (PMID 24763305, 2014). "However, TT genotype in ERCC2 Lys751Gln polymorphism may significantly decrease the risk of glioma in the Caucasian population with combined OR of 0.87 (0.78–0.97), but not in the Chinese population." (PMID 24763305, 2014). "Studies have shown that ERCC2 expression increases in glioma and colon cancer cells resistant to cisplatin." (PMID 40777111, 2025). "We collected eligible studies together to evaluate the association between ERCC1, ERCC2, XRCC1, and XRCC3 polymorphisms and glioma risk in the present study." (PMID 39834980, 2024). "We identified 30 eligible studies investigating the PubMed records (up to January 2024) via a mishmash of the subsequent terms: brain tumors, glioma, glioblastoma, gene associations, SNPs, XRCC1, XRCC3, ERCC1, and ERCC2." (PMID 39834980, 2024). "This comprehensive meta-analysis declared a significant association between ERCC2 rs13181, XRCC1 rs25487, and the risk of glioma." (PMID 39834980, 2024). "Our meta-analysis included 30 articles and thus constituted a wide-ranging evaluation of the relationships of ERCC1 C8092A, ERCC2 Lys751Gln, XRCC1 Arg399Gly, and XRCC3 T241M polymorphisms with the risk of glioma in various populations." (PMID 39834980, 2024). "We conducted a comprehensive meta-analysis with the aim of investigating the ERCC1 (rs3212986), ERCC2 (rs13181), XRCC1 (rs25487), and XRCC3 (rs861539) genes to see if there are any risk factors for glioma susceptibility." (PMID 39834980, 2024). "We conducted a comprehensive meta-analysis to investigate the ERCC1 (rs3212986), ERCC2 (rs13181), XRCC1 (rs25487), and XRCC3 (rs861539) genes to see if they are any risk factors for glioma susceptibility." (PMID 39834980, 2024). "Variations in genes involved in DNA repair, cell cycle, metabolism, and inflammation pathways have been recognized as a key basis of inherited glioma susceptibility, such as PRKDC, XRCC1, PARP1, ERCC1, ERCC2, EGF, and IL13." (PMID 36733406, 2023). "Other loci were found altered such as Aldehyde dehydrogenase 2 (ALDH2) and isocitrate dehydrogenase 2 (IDH2), that was found to predispose to cervical carcinoma and glioma respectively as well as BCL3, AKT2 and ERCC2 for which polymorphisms were shown to be associated with lung carninoma." (PMID 31105870, 2019). "Next, stratified analyses for different types of glioma including glioblastoma multiforme and nonglioblastoma multiforme were performed in ERCC2 Lys751Gln polymorphism." (PMID 24763305, 2014). "Thus, a screening test that will include the ERCC1 (rs3212986), ERCC2 (rs13181), XRCC1 (rs25487), and XRCC3 (rs861539) genes may well be helpful for the prevention and earliest treatment of patients with glioma susceptibility." (PMID 39834980, 2024). "Likewise, seven studies reported ERCC2 Lys751Gln, including 2,758 glioma cases and 3,847 controls." (PMID 24763305, 2014). "We have identified and functionally validated that Ercc1, Ercc2, Mutyh and Pnkp participate to TMZ resistance in gliomas." (PMID 26336131, 2015).
glioma (continued). "ERCC2 is involved in nucleotide excision repair (NER), which may be related to the repair of DNA damage in glioma cells." (PMID 37208656, 2023).
skin cancer (15 papers, 2011 to 2025). "The p.K751Q heterozygous mutation in the ERCC2 gene is a single-nucleotide polymorphism (rs13181) missense mutation, which is associated with the risk of various tumors such as lung, bladder, breast, and skin cancers, and low risk indicators." (PMID 41256322, 2025). "Our article indicated that people with mutations in the genes FokI (rs2228570), ERCC2 (rs13181), MMP1 (rs475007), and ERCC2 (rs238406) were more likely to have skin cancer." (PMID 36874118, 2023). "For example, ERCC2 gene mutations have been shown to indirectly increase the risk of SC, and the Melanocortin receptor 1 (MC1R), which encodes melanocyte-stimulating hormone (MSH) receptors, has also been shown to be a risk factor for skin cancer." (PMID 36874118, 2023). "Furthermore, ERCC2 (XPD) is involved in nucleotide excision repair (NER) and chromosome segregation, which alterations have been associated with an increased risk of skin cancer." (PMID 27057633, 2016). "Furthermore, the ERCC2 Asp312Asn polymorphism is associated with bladder, esophageal, and gastric cancers, but not with breast, head and neck, lung, prostate, and skin cancers, and non-Hodgkin lymphoma." (PMID 28489582, 2017).